INS (insulin)
Diseases named in the same sentence as INS in open-access papers (continued):
Sharing a sentence is not in itself a finding about the gene and the disease.
diabetes (continued). "In obesity, adipose tissue becomes resistant to insulin-mediated inhibition of lipolysis, thereby increasing aP2 secretion, which leads to increased hepatic glucose output and diabetes." (PMID 36818396, 2023). "Diminished skeletal-muscle glucose uptake and attenuated skeletal-muscle insulin sensitivity are important precursors for the pathogenesis of type 2 diabetes mellitus." (PMID 36837888, 2023). "Type 1 diabetes mellitus (T1D) is a chronic autoimmune disease in which autoreactive T cells attack insulin-producing pancreatic β-cells." (PMID 37766096, 2023). "Through these gatherings, the person with diabetes learned how to travel with her insulin supplies and she learned about how to better manage her diet." (PMID 37535407, 2023). "The overuse of islet cells eventually exhausts the pancreas, reducing its ability to produce insulin and ultimately leading to diabetes mellitus." (PMID 37810881, 2023). "At 6 months, serum concentrations of biomarkers of diabetes (insulin, IGF-I) and lipid metabolism (total cholesterol, HDL-cholesterol, and triglycerides) were not significantly affected by the increase in physical activity." (PMID 36631905, 2023). "One research direction in this field is antigen vaccination (with oral insulin or peptides) and stem-cell-based replacement therapies to prevent and reverse diabetes autoimmunity." (PMID 37629520, 2023). "As a typical metabolic disease, diabetes mellitus (DM) is related to either impaired insulin secretion or insulin resistance, with the majority of DM patients being type II diabetes associated with pancreatic β-cell abnormalities and insulin resistance." (PMID 37687083, 2023). "Patients presenting on-hours had a higher proportion of patients with diabetes (including those on insulin therapy), arterial hypertension, hypercholesterolemia, prior PCI, and prior coronary artery bypass grafting (CABG)." (PMID 35789430, 2023). "The fuzzy logic approach is less commonly used and involves modulating insulin delivery based on rules which reflect the reasoning of experienced diabetes practitioners." (PMID 37289734, 2023). "Anti‐insulin antibody‐mediated dysglycaemia in insulin‐treated diabetes was intensively studied in the era of widespread animal insulin use, and to some extent later when insulin analogues came to predominate." (PMID 37562398, 2023). "miR-155, when altered in diabetes, affects the insulin sensitivity in the liver, adipose tissue, and skeletal muscle." (PMID 37373398, 2023). "In this journey, there are various treatments available in market to manage diabetes mellitus such as insulin, GLP-1 agonist, biguanides, sulphonyl ureas, glinides, thiazolidinediones targeting the receptors which are discovered decade before." (PMID 36782201, 2023). "Diabetes mellitus (DM), a complex and common metabolic disorder, occurs when the β cells of islets are unable to synthesize sufficient insulin or when the body is unable to use the insulin effectively." (PMID 36675654, 2023). "Esculetin is believed to have the potential to treat diabetes and its complications by promoting glucose degradation, inhibiting glucose production, increasing insulin levels, and improving insulin sensitivity." (PMID 37800835, 2023). "In order to improve the curative effect of treatment, control insulin levels, and reduce the mortality rate of diabetes, the artificial closed-loop system, namely the artificial pancreas system, is widely studied by researchers." (PMID 36987204, 2023). "With these data in mind, the present study compared the effects of commonly prescribed medications for diabetes (dapagliflozin, insulin, and bromocriptine) on nicotine intake in female and male rats displaying insulin resistance." (PMID 38389818, 2023). "Insulin injection is currently one of the most commonly used approaches for the treatment of diabetes mellitus." (PMID 37514488, 2023).
diabetes (continued). "There is also a link to diabetes as insulin signaling lowers LPS-induced CXCL1 expression in gingival fibroblasts, and short-chain fatty acid can lower cytokine-induced expression of CXCL1 and CXCL2 in HSC2 cells and gingival fibroblasts." (PMID 37762294, 2023). "This is consistent with the other studies, which have shown lower use of diabetes technology, both insulin pump and CGM, in NHB and Hispanic youth compared to the White youth." (PMID 40303258, 2023). "This study aimed to evaluate adherence to and efficacy of CGM in improving diabetes management in insulin-treated older adults with T2DM." (PMID 37993898, 2023). "The study also reported an increase in adipose tissue insulin resistance from lean to obese individuals and from individuals with normal glucose tolerance to impaired glucose tolerance and type 2 diabetes mellitus." (PMID 38034219, 2023). "Diabetes mellitus (DM) is a chronic metabolic disorder characterized by hyperglycemia due to inadequate insulin secretion, resistance, or both." (PMID 37239956, 2023). "A previous study from India collected information regarding the barriers to optimum treatment utilization by people living with diabetes in India but was limited to insulin usage." (PMID 37059974, 2023). "These patients tend to have high blood insulin levels before the onset of diabetes and higher insulin resistance than their peers." (PMID 37793000, 2023). "By 12 months post-surgery, nearly half (48.8%) of the cohort had discontinued diabetes medications and the average insulin dose for those still requiring it had decreased by 73.6%." (PMID 36827391, 2023). "Many individuals with diabetes, especially type 1, are concerned about weight gain as insulin therapy can lead to increased fat storage." (PMID 38041170, 2023). "Type 2 diabetes mellitus (T2DM) is characterized by high insulin concentrations, at least at its early stages due to insulin resistance, which contrasted the lack of insulin in T1DM." (PMID 36942499, 2023). "In this study, we found that impaired insulin secretion is involved not only in the development of PTDM but also in diabetes remission in patients with pre-existing diabetes." (PMID 37424863, 2023). "Studies have found that insufficient insulin secretion or output disorders will eventually lead to diabetes." (PMID 37143582, 2023). "While men typically get diagnosed with diabetes at a lower body mass index than women, other evidence suggests women remain more insulin sensitive despite weight gain due to their greater ability to expand subcutaneous storage capacity." (PMID 37671124, 2023). "This proves that insulin has generalized hormonal effects in addition to its well-known ability to lower blood sugar, which explains why diabetes affects various tissues." (PMID 37241737, 2023). "In this essay, we will examine how imbalances in insulin and leptin can lead to obesity and diabetes." (PMID 37600709, 2023). "In the context of diabetes management, predicting future glycemic levels is a critical task that enables patients to adjust their insulin dose and take necessary actions to prevent hypo- or hyperglycemia." (PMID 37050725, 2023). "Diabetes mellitus is a serious metabolic disease characterized by persistent hyperglycemia resulting in impaired insulin resistance, insulin sensitivity, or both due to changes in the metabolism of carbohydrate, protein, and lipid." (PMID 38107140, 2023). "Further studies need to be performed which distinguishes not only by the type of diabetes, but also glycemic control, insulin treatment and the duration of diabetes." (PMID 37180793, 2023). "SNARE proteins are involved in insulin granule exocytosis, but less is known about their relevance to vascular health in diabetes." (PMID 36902363, 2023). "There were significant differences in age, percentage of participants with T1D, diabetes duration, systolic BP, diastolic BP, total cholesterol (TC), triglycerides (TG), percentage of participants treated with insulin." (PMID 37194402, 2023).
diabetes (continued). "Substitution of the “Diabetes mellitus on insulin” component with HbA1C: hemoglobin ratio in RCRI score would put an additional 687 patients in the intermediate or high-risk category." (PMID 37035307, 2023). "While this gene is involved in thermal reception, it is also involved in taste perception, and it is also involved in diabetes and insulin secretion." (PMID 37759745, 2023). "In mice, harmol crossed the blood-brain barrier poorly, but improved glucose homeostasis and insulin sensitivity in a model of diet-induced obesity and diabetes, and delayed neuromuscular degeneration in old mice." (PMID 37188705, 2023). "Family history of diabetes, quality of and access to health care, differences by race/ethnicity in insulin sensitivity, diet quality, and minimal physical activity are some of the risk factors for T2D." (PMID 37313442, 2023). "CircGlis3, a β-cell-derived exosomal circRNA, has been shown to play a role in lipotoxicity-induced β-cell disorder and development of diabetes through suppression of insulin secretion and cell proliferation." (PMID 36911697, 2023). "Feature extraction was performed on the PIMA Indian diabetes dataset, considering information such as the number of pregnancies, glucose levels, insulin levels, blood pressure, and age of the patients." (PMID 37264332, 2023). "Diabetes mellitus (DM) is the most common endocrine disorder caused by insulin production deficiency (T1DM) or a combination of insulin resistance action and insulin secretion from the pancreas (T2DM)." (PMID 37893747, 2023). "During the initial training, healthcare teams or diabetes educators should familiarize the patient with the scent of insulin, enabling them to detect any potential leakage." (PMID 38093983, 2023). "The study population had high access to diabetes technology, where use of continuous glucose monitors was 83.6% and insulin pump use was 68.1%." (PMID 38004219, 2023). "Malvidin, malvidin 3-glucoside, and malvidin 3-galactoside, which are all components of blueberry anthocyanin extract, were discovered by Herrera-Balandrano and co-works to be capable of inhibiting diabetes hyperlipidemia and decrease insulin levels." (PMID 37242519, 2023). "Various stages of pre-diabetes are believed to reflect the gradual changes in glucose and insulin metabolism leading to T2D." (PMID 36709226, 2023). "Another study reported that gut-expressed bitter taste receptors stimulate the secretion of GLP-1 in endocrine cells, which leads to the secretion of insulin in the pancreas and affects the reduction of blood glucose levels in mice with diabetes." (PMID 36768516, 2023). "Over 90% of cases are type 2 diabetes mellitus (T2D), a disorder marked by defective insulin secretion by pancreatic β-cells and the inability of insulin-sensitive tissues to respond to insulin." (PMID 38003703, 2023). "Patients with this type of diabetes need to monitor their blood glucose levels regularly and self-administer insulin in the form of an injection." (PMID 37568877, 2023). "People with T1D presumably need comprehensive diabetes self-management training on issues including insulin dosing, meal content, exercise, and fast-acting carbohydrates to adequately process the program’s content." (PMID 37788058, 2023). "Alternatively, managing diabetes can require drawing blood to measure blood sugar levels or injecting insulin, which in public spaces can be mistaken for drug abuse and draw unwanted attention." (PMID 37383944, 2023). "Absorption of therapeutic peptides like glucagon-like peptide or insulin for diabetes therapy upon oral administration is highly restricted by the tight junction (TJ) proteins interconnecting the cells comprising the intestinal epithelium." (PMID 40838052, 2023). "Several approaches are used for diabetes treatment: via the intake of healthy food and diet control, using insulin injections, or standard hypoglycemic chemical drugs." (PMID 36677055, 2023).
diabetes (continued). "The primary goal of studying islet transplantation in the omentum is to reinstate insulin production in patients with diabetes to eventually eradicate the need for immunosuppressive medications." (PMID 37965322, 2023). "JNK is a subfamily of MAPKs and plays a critical role in the regulation of insulin signaling, inflammation, apoptosis, and caspase-3 activity in diabetes and the upregulation of pro-inflammatory cytokines such as MCP-1, IL-6, IL-8, and TNF-α in AD pathology." (PMID 38006400, 2023). "Diabetes mellitus (DM) is one of the most common metabolic diseases which is characterized by hyperglycemia due to dysfunction of insulin secretion, insulin resistance, or both." (PMID 37818560, 2023). "For instance, patients with obesity and/or type 2 diabetes mellitus had lower insulin concentrations in the cerebrospinal fluid despite higher levels of this hormone in peripheral plasma." (PMID 37025701, 2023). "This study investigates the effectiveness of telemedicine in managing glucose levels in insulin-treated diabetes patients compared to standard care." (PMID 38077677, 2023). "Diabetes mellitus is a group of metabolic illnesses categorized by hyperglycemia that is primarily induced due to inadequate insulin release or synthesis." (PMID 36838577, 2023). "The patient had a history of hypertension, hyperlipidaemia, insulin usage for type 2 diabetes mellitus, percutaneous coronary intervention for unstable angina pectoris, and postoperative lobectomy for right lung cancer." (PMID 36732803, 2023). "Impaired insulin secretion and varied degrees of peripheral insulin resistance is the major pathogenesis mechanism of diabetes." (PMID 37700304, 2023). "Diabetes mellitus (DM) is a chronic disease characterized by abnormal blood glucose levels resulting from impaired insulin action and/or insulin secretion, usually both." (PMID 36979949, 2023). "Unstable glycaemia in insulin‐treated diabetes usually relates to suboptimal insulin management skills, psychological factors, and/or variable insulin absorption." (PMID 37562398, 2023). "They manage diabetes medications, including insulin, and tailor treatment plans based on blood glucose levels, HbA1c targets, and individual patient characteristics." (PMID 37746454, 2023). "In summary, our findings emphasize telemedicine's effectiveness in managing FBS levels, a vital aspect of diabetes control among diabetic patients using insulin therapy in primary care settings." (PMID 38077677, 2023). "For example, in streptozocin induced diabetes, the inhibition of D6D is much stronger than inhibition of D5D, indicating that D6D more strongly depends on insulin than D5D." (PMID 37545582, 2023). "Diabetes mellitus is a chronic and complex metabolic disorder that results from a defect in insulin secretion, action, or both." (PMID 37349801, 2023). "On the one hand, this characteristic facilitates the setup of experiments and investigations related to insulin treatment and the potential reversal of diabetes." (PMID 37859703, 2023). "Traditional MODY criteria (age at diabetes diagnosis less than 25 years, non-insulin requiring and a parent affected with diabetes) had a PPV of 58%, yet missed even more cases (63%) compared with the biomarker pathway." (PMID 37794142, 2023). "Diabetes mellitus (DM) is a chronic metabolic condition described by persistent hyperglycemia due to the incapability of the pancreas to produce enough insulin, or the organ cannot use the produced insulin (insulin resistance), or a combination of both." (PMID 37570720, 2023). "When evaluating glycemic outcomes, race remained a significant cofactor despite controlling for age, duration of diabetes, sex, insurance status, and insulin administration type." (PMID 40303248, 2023). "Given the importance of excessive inflammation in diabetes, we show that copper can reduce insulin resistance mediated by inflammatory cytokines in muscle cells." (PMID 37713400, 2023).
diabetes (continued). "Our results thus cumulatively provide evidence of the protective effect of higher childhood BMI on insulin secretion and sensitivity, which are crucial intermediate diabetes traits." (PMID 36798216, 2023). "GAS5 lncRNA is decreased in the serum of patients with diabetes and individuals with low GAS5 levels are more susceptible to develop diabetes, as its reduction decreases the insulin secretion and increases the β-cell dysfunctionality." (PMID 37670346, 2023). "The majority of participants used oral diabetes medication only (45.63%), with 18.58% using any insulin." (PMID 37775738, 2023). "The PI3K/AKT signaling pathway mediated by insulin is essential in the pathogenesis of diabetes mellitus." (PMID 38231654, 2023). "Further developments, including synthetic short- and long-acting insulin, portable blood sugar monitoring and insulin pumps, have all improved diabetes management." (PMID 37176684, 2023). "The results showed significant differences among body weight and blood glucose level from the 1st to 28th day of diabetes induction in rats as well as the insulin level of all six groups (G0, G1, G2, G3, G4 and G5)." (PMID 37569180, 2023). "First-line medications most often used to treat diabetes were metformin (58.1%), sulfonylurea (20.9%), and insulin (18.6%)." (PMID 36915157, 2023). "In patients with diabetes, the conventional approach to controlling serum blood glucose involves subcutaneous insulin administration or the use of oral medications that increase insulin production." (PMID 37446104, 2023). "Diabetes mellitus is a chronic hyperglycemic condition that occurs either when the pancreas does not produce enough insulin or when the body cannot effectively use insulin to regulate glucose." (PMID 37174741, 2023). "The line chart includes 5 common clinical characteristics of gender, serum phosphorus, UACR, duration of diabetes, and use of insulin." (PMID 37008912, 2023). "To date, there have been no recommendations or guidelines for the use of continuous subcutaneous insulin infusion (CSII) in Type 2 Diabetes Mellitus (T2DM)." (PMID 36676765, 2023). "The overexpression of IGFBP2 by an adenovirus reversed diabetes in insulin-resistant ob/ob and diet-induced obese mice." (PMID 37509659, 2023). "Of the diabetes medications that were examined, insulin was the only drug that normalized the high levels of nicotine intake in HFD-fed rats to RD control levels." (PMID 38389818, 2023). "In August of 1921, Nicolae Paulescu presented for first time the effect of pancreine (later called insulin), which was extracted from animal pancreas, on diabetes symptoms." (PMID 36678915, 2023). "The induction of diabetes by partial destruction of pancreatic β cells resulted in a significant (p < 0.05) decrease in serum insulin concentration and HOMA-β scores, as observed in the DBC group." (PMID 38203195, 2023). "Diabetes mellitus is a widespread metabolic disorder where the body experiences elevated blood glucose levels due to either insufficient insulin production or the body’s impaired ability to use insulin." (PMID 38203517, 2023). "Despite the advances in insulin formulations and technologies used to control diabetes, HU continues to affect a significant proportion of patients with diabetes on insulin." (PMID 37964960, 2023). "About 10% of people with diabetes have type 1 diabetes mellitus (T1DM)—the disease caused by autoimmune pancreatic β-cells destruction, therefore it must be treated with exogenous insulin injections." (PMID 37142663, 2023). "All studies assessed T2D based on FBG levels, while two studies additionally assessed T2D with HbA1c and insulin levels (35.37) and the South Asian Biobank study additionally used high glucose levels and diagnosed diabetes." (PMID 37015791, 2023). "Administration of recombinant PON1 to mice prior to streptozotocin-induced diabetes resulted in a decreased incidence of diabetes and higher circulating insulin levels." (PMID 38247481, 2023).